APOE (apolipoprotein E)
Diseases named in the same sentence as APOE in open-access papers (continued):
Sharing a sentence is not in itself a finding about the gene and the disease.
COVID-19 (continued). "Following this premise, two large studies of patients with European-ancestry from the UK Biobank (UKB) cohort reported that individuals with APOE ε4∗ε4 genotype had an increase in the risk of developing severe COVID-19 and a four-fold increase in mortality after testing positive for COVID-19." (PMID 34179542, 2021). "Conflicting with our hypothesis, some investigations point ApoE as a causative for complications during COVID-19 clinical evolution." (PMID 34179542, 2021). "In logistic models, ApoE e4e4 genotype was associated with increased risks of test positivity (OR = 2.24, 95% CI: 1.72–2.93, p = 3.24 × 10−9) and of mortality with test-confirmed COVID-19 (OR = 4.29, 95% CI: 2.38–7.72, p = 1.22 × 10−6), compared to e3e3s." (PMID 32623451, 2020). "Particularly, studies on genetic susceptibility with Apolipoprotein E and glutathione family genes seem to be especially promising for public health strategies, since previous studies performed in these populations showed a high prevalence for the genotypes associated with a higher risk of COVID-19." (PMID 36901217, 2023). "In summary, the inconsistency in the findings related to the association between APOE gene polymorphism and COVID-19 risk and severity may be due to the differences in the genetic characteristics and age of the included subjects, the case definitions and the number of subjects employed." (PMID 36089575, 2022). "In an attempt to pinpoint the causal relationship between ApoE ε4 and COVID-19 susceptibility or severity, a study performed using human-induced pluripotent stem cells (hiPSCs) provided evidence that ApoE ε4 could lead to increased SARS-CoV-2 susceptibility in both neurons and astrocytes." (PMID 35055344, 2022). "Together, these findings may explain why individuals of European-ancestry, who have higher frequencies of haplotypes that confer deficiency in APOE expression, may be at higher risk to COVID-19 severe course, as demonstrated by the current available epidemiology." (PMID 34179542, 2021). "Studies on COVID-19 have uncovered a correlation between the severity of the disease and an impaired reverse cholesterol transport mechanism in individuals with the APOE ε4/ε4 genotype." (PMID 41303587, 2025). "Patients with the APOE e4e4 genotype have a heightened risk of SARS-CoV-2 infection compared to those with the APOE e3e3 genotype, and homozygotes of APOE e4e4 are more likely to experience severe COVID-19." (PMID 40722786, 2025). "Most relevant for COVID-19, lipidated ApoE induced ACE2 movement to GM1 rafts and enhanced virus infection." (PMID 38388172, 2024). "Especially the type 4 allele of the gene for apolipoprotein E (APOE ɛ4) is a major susceptibility factor for AD and COVID-19." (PMID 38393535, 2024). "In human apoE TR mice infected with mouse-adaptive COVID-19, both E2 and E4 mice showed a faster disease progression, increased viral loads and suppressive adaptive immune responses earlier after infection, and poorer survival than E3 mice." (PMID 39660133, 2024). "Among the first genetic variants associated with COVID-19 were polymorphisms within the angiotensin-converting enzyme (ACE1), apolipoprotein E (APOE), and chemokine receptor 5 (CCR5) genes." (PMID 39244150, 2024). "Compared with the control data, LAMA4 and VEGFC were highly expressed in children with myocarditis and COVID-19, whereas APOE and TNFRSF9 were expressed at low levels." (PMID 39026189, 2024). "Analysis of the data from the UK Biobank community cohort indicated that ApoE ε4ε4 homozygotes were 2.31 times more likely to test positive for COVID-19 than ε3ε3 homozygotes." (PMID 36767513, 2023). "There was also downregulation of lipid metabolism-associated genes (FABP4, APOC1, APOE, MARCO) in COVID-19 effector CD8+Tcs." (PMID 37029220, 2023).
COVID-19 (continued). "Further, we analyzed the regulatory effects of different ApoE isoforms on the expression of ACE2, and the balance of the RAS pathway, providing plausible evidence that ApoE4 contributes to severe COVID-19." (PMID 36759834, 2023). "The deficiency in apolipoproteins levels in COVID-19 compared to normal human plasma (NHP) and ICU-ARDS patients was most pronounced for APOA1, APOA2, APOA4, APOC3 and APOE." (PMID 37031181, 2023). "This study provides the first insight into a possible APOE-mediated mechanism of COVID-19 vulnerability and severity." (PMID 36717892, 2023). "COVID-19 patients carrying APOE ε4 also show a significantly higher level of serum pro-inflammatory cytokines than patients with the APOE ε3/ε3 genotype." (PMID 36717892, 2023). "The impact of APOE variants on SARS-CoV-2 infection has been a focus in studies on the mechanistic link between AD and COVID-19." (PMID 36717892, 2023). "To date, the studies that cited APOE’s participation in the COVID-19 manifestations have focused on clinical manifestations, and few studies are showing the role of APOE polymorphism in the genesis of post-COVID-19 cognitive manifestations." (PMID 38137059, 2023). "In this study, out of 1238 variant previously reported to be association with susceptibility and severity of COVID-19, we confirmed 49 variants, corresponding to 18 independent loci, including 3p21.31 locus, ABO, IFNAR2, TNF, APOE, and FOXP4-AS1 gene." (PMID 36531218, 2022). "In this study, we investigated correlations between APOE and immune responses in COVID-19 patients, and determined how APOE and its isoforms regulate SARS-CoV-2 infection in cellular and animal models." (PMID 35915083, 2022). "More comprehensive and systemic studies with multiple approaches are needed to further elucidate how APOE is involved in COVID-19." (PMID 35915083, 2022). "Pooled results demonstrated that polymorphisms in the ApoE, ACE1, TMPRSS2, CCR5, and HLA genes appear to be involved in the susceptibility to and/or severity of COVID-19." (PMID 35793369, 2022). "In conclusion, polymorphisms in the ApoE, ACE1, TMPRSS2, CCR5, and HLA loci appear to be involved in the susceptibility to and/or severity of COVID-19." (PMID 35793369, 2022). "APOE Ɛ4 haplotype (rs7412/rs429358) has been shown to associate with increased susceptibility to SARS-CoV-2 infection and COVID-19 mortality in previous genetic studies." (PMID 36531241, 2022). "HEK293T cells were then loaded with cholesterol (apoE + serum) to better reflect the disease state of COVID-19 with severe symptoms." (PMID 36104427, 2022). "Here, we show that serum concentrations of APOE correlate inversely with levels of cytokine/chemokine in 73 COVID-19 patients." (PMID 35915083, 2022). "Three clusters of complement activation demonstrated a various milieu of ApoE & FH vs C5a & TCC in COVID-19 patients." (PMID 35953544, 2022). "In turn, as has been shown, the APOE gene polymorphism can affect susceptibility to SARS-CoV-2 infection, COVID-19 severity and mortality." (PMID 36292001, 2022). "COVID-19 has also been shown to damage the microvasculature of the brain and lead to enhanced expression of APOE at the barriers of the CNS: the choroid plexus and in astrocytes, which participate in formation of the BBB." (PMID 34949230, 2021). "Multivariate analysis showed that high NEFAs, low ApoE and low HDL cholesterol concentrations are significantly associated with COVID-19 status, independently of body mass index, baseline severity (SOFA score) and acute phase response (CRP level)." (PMID 34031519, 2021). "Multiple linear regression showed that COVID-19 status was associated with high plasma NEFAs, low HDL cholesterol levels and low ApoE plasma concentrations, independently from body mass index (BMI), SOFA score and plasma CRP." (PMID 34031519, 2021).
COVID-19 (continued). "While there is previous evidence for ApoE effects on viral infections, further investigations to understand the biological mechanisms linking APOE genotypes and COVID-19 severity are needed." (PMID 33800954, 2021). "Next, we looked into the prevalence of APOE4 in two COVID-19 cohorts, which we sequenced for APOE genotype status, and matched the genotypes with histological results from neuropathological autopsy material, or clinical records, respectively." (PMID 34949230, 2021). "Contrarily, individuals from Africa and East Asia regions, both carrying lower frequencies of expression-modifying haplotypes of APOE, have reported fewer numbers of severe cases and smaller rates of mortality of COVID-19." (PMID 34179542, 2021). "Further studies are needed to validate these results in another cohort and to understand the mechanisms linking ApoE genotypes to COVID-19 severity." (PMID 32983152, 2020). "Although further investigations are surely needed to understand the biological mechanisms linking ApoE genotypes to COVID-19 severity in depth, it is important to highlight some relatively understudied role of APOE4." (PMID 32839380, 2020). "Future studies should aim to clarify the relationships between APOE ε4, COVID-19, and cerebral vascular dysfunction and AD." (PMID 33380345, 2020). "Independent replications are needed to confirm our findings and mechanistic work is needed to understand how ApoE e4e4 results in the marked increase in vulnerability, especially for COVID-19 mortality." (PMID 32623451, 2020). "ApoE e4e4 homozygotes were more likely to be COVID-19 test positives (OR = 2.31, 95% CI: 1.65 to 3.24, p = 1.19 × 10–6) compared to e3e3 homozygotes." (PMID 32451547, 2020). "Further investigation is needed to understand the biological mechanisms linking ApoE genotypes to COVID-19 severity." (PMID 32451547, 2020). "A recent UK study reported that there was a higher prevalence of COVID-19 in people who were carriers of APOE ε4." (PMID 33380345, 2020). "Patients with devere and mild COVID-19 exhibited substantial reduction in the expression of FABP4, APOC1, APOE, C1QB, and NURP1, all associated with interstitial and macrophage cluster-0." (PMID 33138195, 2020). "This difference could potentially impact the severity of COVID-19 in individuals carrying the APOE ε4/ε4 genotype." (PMID 41303587, 2025). "While sex, vaccination and APOE genotype have been associated with COVID-19 severity, our analyses showed no consistent effects for these variables." (PMID 39885359, 2025). "While it is an advantage to be able to perform COVID-19-related studies without replicating virus and outside a BSL-3 facility, we recognize that more severe effects and more profound apoE isoform-dependent effects would likely be seen following mouse-adaptive COVID-19 viral inoculation." (PMID 39660133, 2024). "First, using the most recent COVID-19 phenotype and AD GWASs allowed us greater power to detect associations between COVID-19 PRSs and AD that were independent of age, sex, or APOE genotypes." (PMID 39764106, 2024). "There is a link between APOE-ε4 and the severity of COVID-19." (PMID 38393535, 2024). "We observe an upregulation of genes involved in antiviral response pathways, including OAS1 that mediates RNase L pathway, IFIT1, and APOE at the upper respiratory airway of COVID-19-infected Ghanaians compared with a relevant publicly available dataset (GSE166530) from an Indian COVID-19 cohort." (PMID 38375062, 2024). "ApoE isoforms may affect microglial activation and neuroinflammatory state of the brain and thus modulate pathogenesis of both COVID-19 and AD." (PMID 37927339, 2023). "Accordingly, we found that COVID-19 patients had higher plasma ApoE concentration." (PMID 36902035, 2023).
COVID-19 (continued). "The cognitive loss in neurological disorders has an important metabolic basis and involves risk factors with APOE that can lead to the cognitive loss present in AD and MS as well as increase susceptibility to viral infections, such as during SARS-CoV-2 with COVID-19." (PMID 38022638, 2023). "Interestingly, an increasing number of studies have found that AD and COVID-19 share the same gene loci, that is, OAS1 and APOE ε4, and are genetically regulated with an increased risk for severity." (PMID 37361546, 2023). "The APOE genotype of 201 COVID-19 patients (101 patients with asymptomatic to mild form of the disease as the control group and 100 patients with severe to critical illness without any known background risk factors as the case group) were detected via multiplex tetra-primer ARMS-PCR method." (PMID 35931737, 2022). "APOE genotyping by Sanger sequencing and real-time PCR showed that 71.83% subjects are APOE ε3/ε3 (the ε3 carriers), and 28.17% subjects are APOE ε3/ε4 or ε4/ε4 (the ε4 carriers) in a Chinese cohort of 142 COVID-19 patients excluding APOE ε2 carriers." (PMID 35915083, 2022). "Specifically, we identified three markers, apolipoprotein E (APOE), membrane-spanning 4-domain subfamily A member 4A (MS4A4A), and protein-tyrosine kinase 2-beta (PTK2B), which displayed the same trend in AD and COVID-19 compared to the control group according to our AD-high-risk scores." (PMID 36211330, 2022). "On the first visit, the concentration of antibodies to COVID-19 and APOE genotype was measured." (PMID 36292001, 2022). "This increased incidence of severe COVID-19 might be due to the regulation of proinflammatory pathways and lipoprotein function being affected by the ApoE e4 genotype." (PMID 35618891, 2022). "In the brain autopsy material of COVID-19 patients, perivascular microhemorrhages were found to be more common in APOE ε4 carriers, suggesting that some of these effects may be mediated by increased cerebrovascular damage." (PMID 36292001, 2022). "Multiple molecular mechanisms may underlie the possible relationship of APOE polymorphisms with SARS-CoV-2 infection and COVID-19 severity, and some of the mechanisms remain speculative." (PMID 36089575, 2022). "Apolipoprotein E4 (apoE4) occurs high in frequency in individuals of African descent as compared to Europeans or Asians and was considered to be a predictor of rapid and severe illness in COVID-19, as it leads to robust immune responses." (PMID 36160776, 2022). "Moreover, data regarding polymorphisms in 8 genes (HLA, ABO, ACE1, ACE2, APOE, CCR5, TMPRSS2, and IFITM3) were meta-analyzed in relation to the risk of infection and severity of COVID-19." (PMID 35793369, 2022). "In the COVID-19 group, coagulation factor XIII A chain (F13A1) and contactin associated protein 2 (CNTNAP2) exhibited the strongest upregulation, with CD14, C1QC, cytochrome C oxidase subunit 7C (COX7C) and (APOE) being increased in the AD group." (PMID 36211330, 2022). "Among the known genetic risk factors for CNS injury, the potential contribution of the apolipoprotein E (ApoE4) genotype should be determined, especially given that cerebrovascular damage may be a prominent characteristic of brain injury in COVID-19 patients." (PMID 33115334, 2021). "The aim of this study was to shine new light on the influence of APOE genotypes in predicting poor prognosis of COVID-19, such as severity and mortality, through an examination of allelic frequencies of the variants that can alter patterns of this gene expression in lung tissues." (PMID 34179542, 2021). "In addition to ApoA-I, most of the apolipoproteins classically associated with HDLs were less abundant in COVID-19 HDL particles, including ApoA-II, ApoC-I, II, III, IV, ApoA-IV, ApoC-I, ApoJ, Apo(a), ApoE, ApoM, ApoD, ApoB100 and ApoF." (PMID 33504824, 2021).
COVID-19 (continued). "Although ApoE is found on certain HDL subfractions where it facilitates reverse cholesterol transport, our results suggest that ApoE4 affects susceptibility to severe SARS-CoV-2 infection and mortality from COVID-19 independently of HDL-cholesterol levels." (PMID 33667465, 2021). "Therefore, while ApoE can have independent effects on COVID-19 severity, it is also important to consider the implications of ApoE4 co-morbidities on SARS-CoV-2 infection." (PMID 33800954, 2021). "Apolipoprotein E ε4 allele (APOE4) has been shown to associate with increased susceptibility to SARS-CoV-2 infection and COVID-19 mortality in some previous genetic studies, but information on the role of APOE4 on the underlying pathology and parallel clinical manifestations is scarce." (PMID 34949230, 2021). "Further studies could help unravel the biological mechanisms linking ApoE genotypes to COVID-19 severity." (PMID 33092637, 2020). "In particular, the SNPs in the host apolipoprotein E (ApoE), angiotensin converting enzyme 1 (ACE1), transmembrane serine protease 2 (TMPRSS2), C-C chemokine receptor type 5 (CCR5) and human leukocyte antigen (HLA) loci have been linked to the susceptibility and/or severity of COVID-19." (PMID 38291512, 2024). "Moreover, the ApoE ε4ε4 allele was found to increase the risk of severe COVID-19, independent of pre-existing dementia, type 2 diabetes, and cardiovascular disease." (PMID 36767513, 2023). "Additionally, a considerable body of evidence indicates that APOE ε4 allele, a well-known AD risk factor, increases the risk of severity and mortality of COVID-19, independent of pre-existing dementia, cardiovascular disease, and type-2 diabetes." (PMID 36717892, 2023). "Notably, another variant that determines APOE isoforms, rs7412, did not pass the significant threshold, probably because this variant mainly contributes to APOE ε2 isoform while COVID-19 is more associated with APOE ε4 isoform." (PMID 36531218, 2022). "In addition, the direct effects of apoE isoforms on COVID-19 severity and the related pathways require further investigations in patients, animals, and cells to better delineate the major underlying mechanisms, thus facilitating the development of targeted interventions." (PMID 36089575, 2022). "Interestingly, within the United Kingdom Biobank, ApoE e4e4 homozygotes were 2.3–4.0-fold more likely to be COVID-19 test positives (OR = 2.31, 95% CI: 1.65 to 3.24) and may relate to co-expression of ApoE e4 and ACE2 within type 2 alveolar epithelial cells." (PMID 32983152, 2020). "Another study showed that APOE interacts with ACE2, inhibiting SARS-CoV-2 cellular entry and inflammation in COVID-19 patients." (PMID 38752789, 2024). "The majority of the proteins associated with cholesterol metabolism, including APOC1, APOH, and APOE, were found to be decreased, except for APOA4, which was elevated in COVID-19 patients." (PMID 38672194, 2024). "APOE interacts with ACE2 inhibiting SARS-CoV-2 cellular entry and inflammation in COVID-19 patients." (PMID 36845144, 2023). "The authors showed that the APOE ε4 allele downregulates ACE2 protein expression in vitro and in vivo and consequently decreases the conversion of Angiotensin II to Angiotensin 1–7, which may introduce a potential mechanism by which APOE ε4 is associated with COVID-19 severity." (PMID 38137059, 2023). "Compared to ApoE ε3 astrocytes, those with ApoE ε4 also exhibited a more exacerbated cellular response, including reactive astrocytes, enlarged size, and increased fragmentation of the nucleus—an indication of cell death, which may facilitate the progression and severity of COVID-19." (PMID 35055344, 2022). "To investigate the relevance of APOE to SARS-CoV-2-induced inflammatory response, we first examined serum APOE and cytokine/chemokine levels in COVID-19 patients." (PMID 35915083, 2022).